CTLA4 (cytotoxic T-lymphocyte associated protein 4)
Diseases named in the same sentence as CTLA4 in open-access papers (continued):
Sharing a sentence is not in itself a finding about the gene and the disease.
melanoma (continued). "Among them, immune checkpoint inhibitors targeting PD-1/programmed death ligand-1 (PD-L1) and cytotoxic T-lymphocyte-associated protein 4 (CTLA-4) has been widely tested and approved as treatment options for solid organ cancers such as non-small cell lung cancer, renal cell carcinoma, and melanoma." (PMID 34408813, 2021). "Similarly, CD80, CTLA4 and CD66 genes that involve in CTLA4/CD80-86 signaling pathway for T cell inhibition were also significantly highly expressed in low risk melanoma patients." (PMID 34040608, 2021). "HSPA7 was found to be a risk factor in the cohort of melanoma patients who received anti-CTLA4 therapy but was found to be a beneficial prognostic factor in the TCGA SKCM cohort, exhibiting no obvious correlation with immune checkpoint expression or the immune response." (PMID 34354698, 2021). "Based on these observations, we investigated the possibility that the difference in clinical benefits between anti-PD-1/L1 and anti-CTLA-4 therapies in patients with MAP2K1/2-mutated melanoma can be used as a biomarker for the selection of the appropriate immunotherapy drug." (PMID 35069558, 2021). "Furthermore, in Icos-deficient mice, antitumor T-cell responses elicited by anti–CTLA-4 are significantly diminished, thereby impairing B16 melanoma rejection." (PMID 33924428, 2021). "The multiple therapeutic antibodies that block immune checkpoints, such as cytotoxic programmed cell death protein 1 (PD1, PDCD1) and T lymphocyte associated antigen 4 (CTLA4), showed great effects in treating non-small-cell lung cancer, kidney cancer, and melanoma." (PMID 33917399, 2021). "ICB therapies, including programmed cell death-1, its ligand, and cytotoxic T-lymphocyte associated protein-4, have been approved for the treatment of multiple carcinoma types, such as advanced melanoma, renal cell carcinoma, non–small cell lung cancer, and BLCA." (PMID 35174161, 2021). "Additionally, SERPINB3 or SERPINB4 mutations are associated with good prognosis in melanoma patients treated with cytotoxic T lymphocyte-associated protein-4 (CTLA-4) blockade." (PMID 34367132, 2021). "These processes might account for the superiority of anti-CTLA-4 therapy over anti-PD-1 therapy in MAP2K1/2-mutated melanomas." (PMID 35069558, 2021). "Preclinically, Sunitinib shows a synergistic antitumor effect with cytotoxic T‐lymphocyte‐associated protein 4 (CTLA‐4) monoclonal antibody (mAb) in melanoma and nonsmall cell lung cancer (NSCLC) immune competent mice by promoting the tumor‐infiltrating lymphocytes activity." (PMID 33510997, 2021). "Combined treatment using inhibitors that target cytotoxic T-lymphocyte-associated protein 4 (CTLA-4) together with PD-1 has achieved significant clinical success in treating various cancers, especially melanoma, and resulted in higher survival rates of patients." (PMID 33466790, 2021). "To date, the US Food and Drug Administration has approved the following 3 ICIs for the treatment for advanced melanoma: ipilimumab (cytotoxic T-lymphocyte-associated antigen 4 [CTLA-4] inhibitor), pembrolizumab, and nivolumab (programmed cell death protein 1 [PD-1] inhibitors)." (PMID 34854905, 2021). "Recent advancements in immunotherapy for melanoma include the blockade of immune checkpoint proteins (ICPs), Programmed Death-1 (PD-1), Programmed Death-Ligand 1 (PD-L1), and cytotoxic T-lymphocyte-associated protein 4 (CTLA-4)." (PMID 33418925, 2021). "We also found 99 patients who received anti‐CTLA4 treatment, including 75 patients with melanoma (43 with TERT mutations and 32 with TERT wild type), 20 patients with breast cancer (all with TERT wild type), and four patients with other cancer types (also TERT wild type)." (PMID 32810393, 2020). "Interestingly, B. fragilis, which is shown to promote CRC carcinogenesis, was found to promote efficacy of cytotoxic T-lymphocyte-associated protein 4 (CTLA-4) blockade in melanoma patients." (PMID 32380712, 2020).
melanoma (continued). "Also, the ratio of CD8+ T cells and Treg cells is linearly associated with tumor necrosis in CTLA-4 blockaded melanoma." (PMID 31968651, 2020). "Indeed, reactivation of endogenous retroviruses (ERVs) by DNMTi enhances susceptibility to anti-cytotoxic T-lymphocyte-associated protein 4 (CTLA-4) ICI therapy in the B16 mouse melanoma model, a model that has been shown to be highly resistant to ICIs." (PMID 32881981, 2020). "A recent study investigated the correlation between circulating B cells and clinical response as well as adverse effects in 39 patients with advanced melanoma receiving anti-PD-1 or anti-cytotoxic T lymphocyte-associated protein 4 (CTLA-4) therapy alone, or in combination." (PMID 33162976, 2020). "Some immunotherapies, such as programmed death-1 (PD-1) and programmed death ligand-1 (PD-L1) inhibitors or cytotoxic T lymphocyte-associated antigen 4 (CTLA4) therapies, have shown an optimistic antitumor effect in melanoma, lung cancer, gastrointestinal cancer and ovarian cancer." (PMID 32463792, 2020). "Thus, MHC-I expression is required for the primary response against CTLA-4 for melanoma, while the primary response to anti-PD-1 is associated with pre-existing IFN-γ-mediated immune activation." (PMID 32864131, 2020). "In some cancers, like non-small-cell lung carcinoma (NSCLC) and malignant melanoma, immunotherapy, such as programmed death-1 (PD-1), programmed death ligand-1 (PD-L1) inhibitors and cytotoxic T lymphocyte-associated antigen 4 (CTLA4) showed outstanding antitumor effects." (PMID 33392251, 2020). "Perhaps unsurprisingly, the combination of anti-CTLA-4 and anti-PD-1 treatments resulted in longer overall survival in patients with advanced melanoma, renal-cell carcinoma, and DNA mismatch repair-deficient/microsatellite instability-high metastatic colorectal cancer." (PMID 32111080, 2020). "Current first-line immunotherapy options in advanced melanoma include either anti-PD1 (anti programmed cell death receptor 1) antibody monotherapy or the combination of ipilimumab (anti CTLA4 antibody—Cytotoxic T lymphocyte-associated protein 4) and nivolumab (anti-PD1)." (PMID 33238616, 2020). "Indeed, there is an association between pre-treatment Foxp3+ T-reg infiltration, followed by a subsequent increase in TILs 3 weeks into treatment in melanoma biopsies which was associated with response to the CTLA4-targeting antibody ipilimumab." (PMID 32133005, 2020). "Moreover, clinical trials indicate that anti-PD-1/PD-L1 combined with cytotoxic T-lymphocyte-associated protein 4 (CTLA-4) blockade exerts a synergistic antitumor effect in melanoma and lung cancer." (PMID 33094098, 2020). "Therefore, we further explored the predictive value of TERT mutation on the efficacy of anti‐CTLA4 treatment in the melanoma group." (PMID 32810393, 2020). "Indeed, melanomas with mutations in IFN-γ signaling are resistant to anti-CTLA-4 blockade; also, this pathway is activated in responders to anti-PD-L1 treatment." (PMID 31968651, 2020). "Using mouse melanoma models, they also demonstrated that overexpression of Wnt/β-catenin is associated with T cell exclusion (resulting in “immune-desert” tumors) and resistance to anti-PD(L)-1 and anti CTLA-4 monoclonal antibody therapies." (PMID 35582435, 2020). "In human melanoma, anti-CTLA-4 therapy was associated with outgrowth of Bacteroides fragilis." (PMID 32899197, 2020). "Recently, new treatment approaches such as antibodies targeting the immune checkpoints T-lymphocyte-associated protein 4 (CTLA-4) or the programmed cell death protein 1 (PD-1) either used alone or as combined immunotherapy remarkably improved prognosis of advanced melanoma." (PMID 32631431, 2020). "The melanoma treatment landscape changed in 2011 with the approval of the first anti-cytotoxic T-lymphocyte-associated protein (CTLA)-4 checkpoint inhibitor and of the first BRAF-targeted monoclonal antibody, both of which significantly improved overall survival (OS)." (PMID 32894202, 2020).
melanoma (continued). "Interestingly, high pretreatment levels of serum VEGF-C were associated with improved progression-free survival in melanoma patients treated with combined inhibition of CTLA-4 and PD-1." (PMID 33217955, 2020). "Furthermore, combination of PS-targeting mAbs with immune checkpoint blockade (anti- cytotoxic T-lymphocyte-associated protein 4 (CTLA-4) or anti-PD-1) has now been evaluated in breast and melanoma syngenic models of cancer in immunocompetent mice." (PMID 32087708, 2020). "A randomized phase II trial (NCT02519322) testing the clinical efficacy of the Nivolumab as monotherapy in combination with the anti-CTLA-4 antibody Ipilimumab in patients with high-risk resectable melanoma was terminated early because of the high incidence of trAEs." (PMID 33256070, 2020). "In 2011 the first ICI, a monoclonal antibody targeting cytotoxic T lymphocyte-associated protein 4 (anti-CTLA-4 or αCTLA-4), was approved for use in advanced melanoma and followed in 2014 by another ICI targeting programmed cell death protein 1 (anti-PD-1 or αPD-1)." (PMID 31409394, 2019). "However, there still remains a role for adjuvant IFN-α in the setting of BRAF wild-type melanomas and in patients at increased risk of cancer immune escape or autoimmune events with CTLA-4 and PD-1 blocking antibodies." (PMID 30725205, 2019). "Metastatic melanoma treated with combination anti-cytotoxic T lymphocyte associated protein 4 (CTLA4) and PD-1 therapy leads to increased response rates and progression free survival compared to single agent immunotherapy in particular for PD-L1 negative patients." (PMID 32083013, 2019). "This study further identifies the existence of specific tumoral neoantigens that create a neoepitope signature as critical for the response to anti-CTLA-4 and overall high mutational load increased the probability of such a signature being present in melanoma patients." (PMID 31406485, 2019). "MITF has been identified as a lineage survival oncogene amplified in malignant melanoma, CTLA-4 expression has been shown to be associated with a more favorable prognosis of patients with CM, and CD74 was identified as a useful prognostic marker associated with OS of patients in stage III melanoma." (PMID 31169496, 2019). "Finally, CTLA-4 gene polymorphisms have been associated to increased susceptibility to multiple types of cancer such as breast, melanoma gastric and colon cancers and cervical carcinomas." (PMID 29682176, 2018). "SNV of CTLA-4 are implicated in clinical response and survival in melanoma patients and, more recently, SNV-1577G > A and SNV CT60G > A were linked to a better response to Ipilimumab in a 173-patients cohort and SNV-1661A > G to the onset of endocrine adverse events." (PMID 30406030, 2018). "Besides, TMB was also illustrated to be associated with clinical response to anti-CTLA-4 and anti-PD-1 in melanoma." (PMID 29793878, 2018). "Furthermore, the accuracy of clinical benefit prediction using actual mutation load in melanoma patients was shown to be 0.6149 and 0.6842 for anti-CTLA-4 and anti-PD-1 treatments, respectively." (PMID 29736260, 2018). "Importantly, CTLA-4 blockade was reported to associate with bowel inflammation in melanoma patients, signifying that its signaling is crucial for the preservation of immune homeostasis in the gut." (PMID 29515971, 2018). "More recently, it was reported that patients with BRAF-mutated melanoma were less likely to require combined PD-1 and CTLA4 blockade than others, reinforcing the view that mutation status may predict response to checkpoint blockade." (PMID 29664013, 2018).
melanoma (continued). "The FDA’s approval of ipilimumab (a monoclonal antibody that targets cytotoxic T-lymphocyte-associated protein 4 (CTL-4) in melanoma) and sipuleucel-T (a personalized immunotherapy treatment for prostate cancers) encourages further immunotherapy research in glioma." (PMID 30366424, 2018). "A phase-II clinical trial in advanced melanoma showed that combining TriMix-matured moDCs presenting melanoma-associated antigens with ipilumab, an antagonistic CTLA4 antibody, resulted in a 6-month disease control rate of 51%, with an overall tumor response rate of 38%." (PMID 29867960, 2018). "In particular, inhibitors of the cytoplasmic serine/threonine kinase BRAF and the immune-checkpoint targeted agents, anti-cytotoxic T-lymphocyte-associated antigen 4 (CTLA-4), and anti-programmed cell death 1 (PD-1) inhibitors have been approved for the treatment of advanced melanoma." (PMID 30693134, 2018). "Programmed death-1/ligand 1 (PD1/L1) inhibitors, and cytotoxic T-lymphocyte-associated protein-4 (CTLA-4) inhibitors have shown significant potential in improving overall survival (OS) in patients with malignant melanoma, non-small cell lung carcinoma, and renal cell carcinoma." (PMID 29747688, 2018). "These target the anti-cytotoxic T lymphocyte-associated protein 4 (anti-CTLA-4) and the anti-programmed cell death protein/protein ligand 1 (anti-PD-1/PD-L1) with antibodies and are being used for the treatment of melanoma, lung cancer, renal cell carcinoma and head and neck tumors." (PMID 28271366, 2017). "In addition, a similar correlation of treatment response and mutation load has been shown for melanoma patients treated with CTLA-4." (PMID 28073373, 2017). "Moreover, several retrospective series have shown that stereotactic radiation and cytotoxic T-lymphocyte–associated antigen 4 (CTLA-4) inhibitor or PD-1 inhibitor can be combined safely for melanoma patients with brain metastases." (PMID 29262592, 2017). "As a single agent in the mouse B16F10 melanoma model and in combination with anti-cytotoxic T-lymphocyte associated protein 4 (CTLA-4) in the EMT-6 mouse breast cancer model, NKTR-214 delivered significantly greater efficacy and improved tolerability than aldesleukin." (PMID 28678791, 2017). "Additionally, we quantified markers associated with immunotherapy response and prognosis in melanoma patients, such as PD-1, PD-L1, CTLA-4 and major histocompatibility complex (MHC) class-II HLA-DR." (PMID 29371976, 2017). "Moreover, in melanoma patients undergoing anti-CTLA4 immunotherapy, circulating PBMC after loss of therapeutic effectiveness had elevated UPR signaling and increased M2-like macrophage population when compared with patient matched PBMC from before therapy." (PMID 29113324, 2017). "In March 2011, the US Food and Drug Administration (FDA) approved ipilimumab, an antibody against cytotoxic T-lymphocyte-associated protein 4 (anti-CTLA-4), and marked the first, approved, immune checkpoint modulator that significantly improved survival in patients with advanced melanoma." (PMID 26981245, 2016). "Currently, there are two that are approved for the treatment of melanoma metastasis: ipilimumab, a monoclonal antibody against cytotoxic T-lymphocyte-associated protein 4 (CTLA-4), and pembrolizumab or nivolumab, antibodies against programmed cell death protein 1 (PD-1)." (PMID 27598148, 2016). "In addition, oncolytic attenuated measles virus encoding single-chain variable regions of CTLA-4 and PD-L1 antibodies have been shown to delay tumor progression and increase survival in an immunocompetent syngeneic mouse model of melanoma." (PMID 28536390, 2016).
melanoma (continued). "Inorder to turn on the immune system against cancer another promishing approach, focused on blocking the negative-regulator of T-cell responses, the cytotoxic T-lymphocyte-associate antigen (CTLA-4), which marked a new era in the treatment of advanced melanoma and oncoimmunotherapy." (PMID 26426340, 2015). "While a number of immunotherapies for melanoma have been associated with significant clinical benefit, including high-dose IL-2 and cytotoxic T lymphocyte antigen 4 (CTLA-4) blockade, clinical response to either of these single agents has been limited to 11-20% of treated patients." (PMID 25992289, 2015). "Using a novel approach to the analysis of SNP results for the CTLA4 gene, we have hypothesized that recognition of melanoma risk genotype profile requires an added dimension of analysis." (PMID 24475110, 2014). "Treatment with ipilimumab, a fully human anti-CTLA-4 antibody approved for the treatment of advanced melanoma, is associated with some immune-related adverse events (irAEs) such as colitis (gastrointestinal irAE, or GI irAE) and skin rash, which are managed by treatment guidelines." (PMID 23521917, 2013). "Thus, we tested the association of variants in FOXP3 microsatellites, CTLA4 SNPs and HLA genotype in 284 melanoma patients and their association with prognosis and survival of patients with melanoma who received adjuvant therapy with IFNa." (PMID 22911710, 2012). "Previous studies of anti-CTLA-4 therapy in melanoma patients have shown an association between clinical activity and treatment-emergent changes in immune cells, such as increased absolute lymphocyte count and changes in specific T-cell populations (e.g., increased frequency of CD8+ cells)." (PMID 22123319, 2011). "The significance of one of these, the cytotoxic T-lymphocyte-associated protein 4 (CTLA4), is indicated by the recent encouraging clinical trials using antibodies directed to this immunosuppressive costimulatory molecule in patients with stage IV melanoma." (PMID 22216283, 2011). "Furthermore, dual blocking of the CTLA-4 and PD-1 immune checkpoints in the neoadjuvant setting with nivolumab and ipilimumab was linked to increased pathologic response and objective response in melanoma." (PMID 40918459, 2025). "Importantly, CTLA-4 blockade not only enhances T-cell activation but has also been associated with an increase in the diversity of the peripheral T-cell repertoire in patients with melanoma." (PMID 40305346, 2025). "The advent of cytotoxic T-lymphocyte-associated protein 4 inhibitors (CTLA4 inhibitors) and programmed death ligand 1 inhibitors (PD-1 inhibitors) has completely revolutionized the management and treatment of various cancers and especially improved the systemic treatment of advanced melanoma." (PMID 38835779, 2024). "Furthermore, clinical research has revealed that immunotherapy employing anti-programmed cell death 1 (PD1) or anti-cytotoxic T lymphocyte-associated protein 4 (CTLA4) antibodies offers significant medical advantages to several melanoma-diseased persons, while medication confrontation persists." (PMID 39777348, 2024). "Therefore, activated anti-tumor immunity, high PDCD1, CD274, and CTLA-4 expression, and enhanced tumor immunogenicity might explain why the low-risk melanoma patients were found to be more likely to benefit from ICI treatment than the high-risk patients." (PMID 37620409, 2023). "For example, ipilimumab (CTLA-4 inhibitor) and pembrolizumab (PD-1 inhibitor) have significantly reduced the risk of recurrences in trials and increased overall survival benefits in their use as adjuvant therapies in patients who completed surgical resection of melanoma lesions." (PMID 37786882, 2023). "Indeed, antibodies neutralizing the PD-1 (Programmed cell death protein 1) and CTLA-4 (cytotoxic T-lymphocyte-associated protein 4) checkpoints yield robust and durable responses for a variety of tumors, including melanomas, non-small cell lung carcinomas, and Hodgkin lymphoma." (PMID 37500611, 2023).